HIF1A (hypoxia inducible factor 1 subunit alpha)
Diseases named in the same sentence as HIF1A in open-access papers (continued):
Sharing a sentence is not in itself a finding about the gene and the disease.
tumor (continued). "The evaluation was through the assessment of tumor volume, histological evaluation, and assessing the overproliferated FRO cells using immunohistochemical staining with hypoxia inducible factor 1α (HIF-1α), p-Akt, VEGF, and transforming growth factor β1 (TGF-β1)." (PMID 33572840, 2021). "Tumor hypoxia and altered pH were shown to reduce bioluminescent signals which led to the development of specific bioluminescent probes for tumor hypoxia using CYP450 reductase and a HIF-1a reporter construct." (PMID 34796317, 2021). "As a tumor suppressor, von Hippel–Lindau tumor suppressor (VHL) protein participates in mediating the ubiquitination and proteasome degradation of hypoxia inducible factor-1α (HIF-1α), inhibiting the development of HCC." (PMID 33869059, 2021). "The stimulation of HeLa cells with 0.3 mM CoCl2 stabilizes endogenous HIF-1α protein, and this raises the level of the target genes to adapt the tumor cells to the hypoxic environment, whereas CAY10585 is a well-known inhibitor of the activity of HIF-1α that decreases the level of the target genes." (PMID 34830219, 2021). "In particular, it has been found that an upregulation of CD73 on both tumor-infiltrating MDSC and Treg could be induced by hypoxia-inducible factor (HIF)-1α." (PMID 33430105, 2021). "In addition, Cyr61 promotes vasculogenic mimicry (VM) formation, thereby promoting tumor growth and metastasis through a αVβ5/FAK/HIF‐1α/STAT3/MMP2 signaling cascade." (PMID 33999512, 2021). "They employed fluorescein isothiocyanate-pimonidazole and Alexa 594 conjugated antibody to detect tumor hypoxia and the expression of HIF-1α, and the control tumors were observed to be very hypoxic (90% positive area) and high expression of HIF-1α (70% positive area)." (PMID 34277702, 2021). "To establish the role of TXNIP and downstream genes HIF1α and IL1β in the biology of cRCC, we have applied immunohistochemistry to tissue multi-arrays containing tumours of patients without detectable metastases at the time of operation." (PMID 34433833, 2021). "Additionally, infection of reovirus-permissive tumor cells and reovirus-resistant tumor cells with the mammalian orthoreovirus (MRV, reovirus) was described to downregulate HIF-1α protein levels." (PMID 34360716, 2021). "However, both HIF1A and HIF2A can also exert tumor-suppressive effects in certain contexts, and the mechanisms driving this functional duality are unclear." (PMID 33654095, 2021). "With the rapid growth of HCC, the tumor cells would respond to the adverse effects of hypoxia, HIF1-α protein level dramatically increases, at this time, highly expressed USP14 would be involved in the maintenance of HIF1-α protein stability." (PMID 34420039, 2021). "In contrast to Hif1α, our data indicate that Hif2α deletion does not significantly alter tumor progression, suggesting that HIF1α and HIF2α target distinct pathways that regulate tumor growth." (PMID 34556788, 2021). "The PH domain of PLD isozymes interacting with these proteins promoted degradation of HIF-1α independent of oxygen concentration and suppressed tumor progression." (PMID 34471223, 2021). "We observed that BATF2 inhibit both HIF-1α and SDF-1α expression in U251 cells and tumour tissues." (PMID 33452462, 2021). "The interaction with stromal cells (SC) induces HIF-1α in CLL cells, through an increased activity of the RAS/ERK1-2, RHOA/RHOA kinase and PI3K/AKT pathways, contributing to drug resistance mechanisms, leukemia survival and tumor propagation." (PMID 34207596, 2021). "Considering the connection of Ca(2+) with RASA4 and HIF1α, we hypothesized that RASA4 may negatively regulate HIF1α signaling and suppress tumor growth." (PMID 34752201, 2021). "In turn, HIF-1α promotes glucose uptake, glycolysis, and lactate secretion through the upregulation of GLUT1 and glycolytic enzymes, thereby fostering cell proliferation and tumor growth." (PMID 34073734, 2021).
tumor (continued). "HIF-1α binds to hypoxia response elements and regulates changes in the expression of different factors, such as VEGF, plasminogen activator inhibitor-1 (PAI-1) and carbonic anhydrase 9 (CAIX), promoting neovascularization and favoring tumor spread." (PMID 33445558, 2021). "Transcription factor HIF-1α could bind with the HKII promoter, initiate HKII expression and eventually promote tumor progression." (PMID 34220956, 2021). "In the hypoxic conditions, the HIF-1α pathway is amplified in tumor cells, which leads to upregulation of CD73 and CD39, two ectonucleotidases involved in adenosine signaling on the surface of both tumor and T cells." (PMID 33168929, 2021). "Among cases with recurrent tissue available, 61% of cases with positive HIF-1α expression in the primary tumor had no expression in the recurrent tumor." (PMID 34736510, 2021). "In lung cancer, overexpression of miR-17 and miR-19 affects the expression of HIF1A, PTEN, BCL2L11, CDKNA, and TSP1, enhancing tumor growth by increasing the permeability of blood vessels, inducing hypoxia, increasing proliferation, inhibiting apoptosis, and stimulating tumor cell migration." (PMID 33803617, 2021). "HIF-1α increases vascular endothelial growth factor (VEGF) expression by affecting the intensification of neoangiogenesis and increased vascular permeability in the tumor." (PMID 34204674, 2021). "The HIF-1α signaling pathway appears to be critical to T cell effector function in the setting of hypoxia, as deletion of HIF-1α in T cells lead to decreased production of IFN-γ, granzyme B, and TNFα by CD8 T cells under hypoxic conditions, facilitating tumor growth." (PMID 34868044, 2021). "First, we explored the impacts of DDP treatment alone, the HIF-1α inhibitor PX-478 treatment alone, and the combined treatments with DDP and PX-478, on in vivo tumor growth, tumor cell apoptosis, and expression levels of EMS, miR-758-3p and WTAP in tumor tissues." (PMID 34081626, 2021). "The reduction of miR-21 gene expression in tumor tissue has probably not been enough to reduce in HIF-1α expression." (PMID 35083006, 2021). "While HIF-1α stabilization within T cells may be beneficial to T cell function and the anti-tumor response, HIF-1α signaling within tumor cells can be problematic, fostering tumor survival within its hypoxic TME." (PMID 34868044, 2021). "Furthermore, several different tumor types have shown a positive correlation between STIM1 and HIF1a levels." (PMID 33919156, 2021). "Some of these molecular alterations found in squamous PDAC, such as inhibition of pancreatic epithelial differentiation genes (HNF4A and GATA6) together with increased hypoxia, HIF1A, C-MYC and WNT, insulin, and PI3K-AKT signaling, promote a metabolic rewiring of tumor cells to glycolysis." (PMID 34503261, 2021). "To ensure that Hif1α deletion in the mammary fat pad did not alter baseline bone microarchitecture, we also scanned tibiae from non-tumor bearing controls (PyMT−) of each genotype." (PMID 34556788, 2021). "Knockdown of HIF-1α in murine hepatocellular carcinomas (Hep3B, HepG2 and SK-Hep-1 cell lines) led to reduced HIF-1-mediated upregulation of CCL28 expression, which can potentially lead to reduced Treg recruitment and Treg-induced tumour angiogenesis." (PMID 33923305, 2021). "HIF-1α is prone to proteolysis in an environment with sufficient oxygen, so the high expression of HIF-1 can be maintained in a relatively hypoxic environment in tumor tissues." (PMID 34671022, 2021). "Meanwhile, Kaplan–Meier analysis showed that high expression of LRRK2 correlates to a better prognosis; knockdown of LRRK2 expression attenuated the proliferation ability of ccRCC tumor cell lines; protein–protein interaction network analysis showed that LRRK2 interacts with HIF1A and EGFR." (PMID 34217264, 2021).
tumor (continued). "It is noteworthy that livers from L‐PDCKO experienced a normoxic condition for availability of oxygen and hence it is expected that HIF‐1α expression will not be up‐regulated as it occurs in hypoxic tumor cells." (PMID 33400855, 2021). "It is suggested that the combination of HIF1α and HKII may regulate the growth of tumor cells by promoting the glycolysis of PCA cells." (PMID 34220956, 2021). "Moreover, HIF-1α/LOX induction and ESM-1 expression, which are involved in tumor metastasis and progression, were enhanced in CD24−/low/CD44+ cells compared to TNBC and RT-R-TNBC cells." (PMID 34502547, 2021). "Apparently, DHA altered neither the phosphorylation of IGF-IR/PI3K/Akt/PTEN and Erk1/2, nor the expression of HIF1α/REDD1 in tumor cells." (PMID 34205996, 2021). "However, stabilized hypoxia-inducible factor 1-alpha (HIF-1α) upregulates the vascular endothelial growth factor (VEGF), promoting abnormal angiogenesis in the tumor and increasing the resistance of tumor cells to RT." (PMID 34829640, 2021). "In various tumor cells, even without DNA binding domain, HIF-1α can promote the ubiquitination of Dicer to facilitate its degradation by autophagy-lysosomal pathway." (PMID 33430279, 2021). "Gene expression analysis of AQP1, HIF-1α, HIF-2α, CXCR4, NMYC, NCAM mRNA reveals major differences between tumors but also between different areas of the same tumor, demonstrating great inter- and intra-tumor heterogeneity." (PMID 33467498, 2021). "LSD1 promotes protein stability and tumor angiogenesis by demethylating the K391 residue and inhibiting HIF-1α downregulation with H2O2 production, which inhibits the hydroxylating activity of PHD2 on HIF-1α with its subsequent ubiquitination." (PMID 34552922, 2021). "Moreover, it has been reported that the expression of HIF1-α is positively correlated with that of HIF1-α target genes, including SNAIL and TWIST, which are involved in tumor metastasis in HCC." (PMID 34420039, 2021). "While HIF1α protein function in NK cells during pathogen infection had not been detailed previously, it was recently explored in tumor-infiltrating NK cells in two studies with comparable results attributed to different mechanisms." (PMID 34396954, 2021). "Also, WB results uncovered that HIF-1α and HECTD2 expression levels were significantly higher in tumor tissues of RCC patients than those in corresponding surrounding non-tumor tissues." (PMID 35004677, 2021). "Although ABCB10 is not an OATP, there is a clear relationship between HIF1α, and the uptake of IR-780 into tumor cells." (PMID 34141613, 2021). "Co-delivery of HIF-1α siRNA and GEM leads to a four-fold decrease in tumor growth." (PMID 34943856, 2021). "However, knockdown of similar [sima in flies; hypoxia-inducible factor-1 alpha, HIF1A (hereafter referred to as Hif-1α) in mammals], which strongly suppresses the upregulation of LDH along with other glycolytic genes, reduces tumor size." (PMID 34240146, 2021). "Based on the role of HIF1α in regulating the expression of genes involved in glycolysis and in KSHV infection, it is possible that the increase in HIF1α observed in the KS sections is due to the tumour undergoing higher rates of aerobic glycolysis." (PMID 33653084, 2021). "In addition to HIF-1α, other proinflammatory factors, transcription factors (NF-κB, STAT3, TNF-α, IL-6), and chemokines promote tumor proliferation by enhancing cancer cell survival, stromal remodeling, angiogenesis, and the metastatic process." (PMID 34204674, 2021). "HIF-1α, VEGFA, and TGF-β1 are important factors for tumor angiogenesis." (PMID 34769497, 2021). "Also, ginsenoside Rg3, a ginseng extract, modulates HIF-1α stabilization, VEGF expression and NF-κB activation upon hypoxia exposure and sensitizes tumor cell lines and xenograft to radiation." (PMID 34041023, 2021).
tumor (continued). "Meanwhile, SLC35A2 was also correlated with “DNA damage Double-strand break repair via homologous recombination”, and “Transcription-Negative regulation of HIF1A function”, which are considered as BRCA-related immunological and cell-cycle pathways that are crucial to tumor development." (PMID 34944621, 2021). "There was a non-significant trend toward a reduction in tumor burden in the brain by Pymt transcript levels in Hif1α−/− PyMT+ mice, and no liver lesions were detected by histological analysis by a certified veterinary pathologist." (PMID 34556788, 2021). "In addition to the tumor-derived factors, hypoxic TME induces HIF-1α dependent glycolysis in MDSCs and promotes their differentiation into immune suppressive tumor-associated macrophages (TAMs)." (PMID 33919732, 2021). "Moreover, hypoxia generated in the microenvironment of the tumor stimulates the expression of VEGF and the VEGF receptor-1-2, in both normal and neoplastic cells through an increase in transcription of HIF-1α and its mRNA stabilization." (PMID 34066606, 2021). "Tumor cells must adapt to this adverse hypoxic environment to sustain lymphangiogenesis and spread to lymph nodes, particularly with the upregulation of VEGF-C mediated by HIF-1α activation." (PMID 34249728, 2021). "As expected, HIF-1α protein was detected in the entire tumor tissue regardless of the distance from tumor vessels, except for necrotic regions." (PMID 34747365, 2021). "Interestingly, this resistance was labile and reversible after hypoxic reversion or HIF-1α inhibition, highlighting the potential relevance to counteract hypoxia in ALK-rearranged tumours harbouring TKI resistances." (PMID 34298636, 2021). "MiR-143 inactivates AKT and inhibits HIF-1α, and VEGF inhibits tumour angiogenesis." (PMID 33865381, 2021). "Next, ELISA analyses showed that HIF‐1α MOCK fibroblasts secreted more CCL5 than HIF‐1α KO fibroblasts, indicating that CCL5 might be the main factor in the tumour promoting effect of HIF‐1α MOCK fibroblasts." (PMID 33943003, 2021). "However, high HIF1α and low p-AMPK expression and their opposite distributions are characteristic for Warburg glycolytic and OXPHOS tumor cells, respectively." (PMID 35029792, 2021). "Finally, hypoxia-inducible factors (HIF-1α and 2α), high-mobility group box 1 protein (HMGB1), extracellular ATP, or tumor-derived ECM components are also potential factors that promote M2 polarization." (PMID 33418996, 2021). "HPV E7 has also been shown to enhance HIF-1α-dependent transcription by inducing dissociation of HDAC1, HDAC4 and HDAC7 from HIF-1α, which might also contribute to tumour angiogenesis." (PMID 34696321, 2021). "Hypoxia drives invasion and migration of tumor cells through processes such as EMT and upregulation of genes involved in extracellular matrix modulation, possibly in a HIF1A-dependent manner." (PMID 33525508, 2021). "Moreover, PcrV treatment did not affect the expression levels of genes (e.g., Cox2, Mmp9, Vegfa, and Hif1a) or proteins (e.g., COX2 and vimentin) related to tumor growth and metastasis, or the metastatic ability of LLC cells." (PMID 34900687, 2021). "In addition, we have also identified a set of genes that are regulated in the opposite way by 7SK and FOXJ3/THRA, including four positive regulators in tumor migration (CXCL1, SYDE1, COL5A1, and HIF1A)." (PMID 33868377, 2021). "Accumulating studies show that HIF-1α induction could facilitate the oncogenic effect of hypoxic condition on RCC angiogenesis and tumor growth by activation of AKT and VEGFR kinases." (PMID 34131104, 2021). "The markedly increased protein expression of MST1, p-LATS1, p-YAP, and YAP (cytoplasm) and the significantly decreased expression of HIF-1α, TAZ, YAP (cells), and YAP (nucleus) in the tumor tissues of the sh-GHET1 group were compared with those of the sh-NC group." (PMID 33869194, 2021).
tumor (continued). "By multiplying the score of staining intensity and percentage of positive cells of each tissue section, we found that HIF-1α and Beclin1 were both highly expressed in OSCC tissues compared with pare-cancer tissue (tumor margin adjacent normal tissues) (p < 0.05)." (PMID 34465721, 2021). "Conversely, among those with no HIF-1α expression in the primary tumor, 19% had positive HIF-1α expression in the recurrent tumor." (PMID 34736510, 2021). "In AML patients, high expression levels of HIF-1α and GLUT1 were associated with lack of response to chemotherapy, probably due to the higher glycolytic metabolism of resistant tumor cells." (PMID 33804775, 2021). "In these tumours, YTHDC2 regulates the expression of tumour promoter genes such as HIF1A." (PMID 33461542, 2021). "The negative impact of hypoxia-induced autophagy in tumor cells is mediated by the nuclear translocation of HIF-1α." (PMID 33422072, 2021). "Thus, siRNAs have been designed for inhibiting tumor-promoting factors including TGF-β, c-Src, and HIF-1α to disrupt PC progression and metastasis." (PMID 34943856, 2021). "In the hypoxic states, HIF-1α is stable and it translocates from the cytoplasm to the nucleus to dimerize with HIF-1β then activate downstream target genes which accelerate cancer progression and promote tumor aggressiveness, including VM." (PMID 31931758, 2020). "Besides, the transcription of E-cadherin is also regulated by Twist, which is regulated by HIF-1α in hypoxia and serves as an important transcription factor promoting EMT of tumor cells." (PMID 32587480, 2020). "Importantly, the number of HIF-1α- and VEGF-positive cells in tumor tissues was significantly reduced following LNT addition (IHC staining results) (the second and third rows)." (PMID 33245358, 2020). "Finally, validation of miRNA18a/HIF1A/PVT1 pathway was checked via reverse transcription-polymerase chain reaction (RT-PCR) assay in both cell lines and clinical tumor samples." (PMID 32226492, 2020). "Additionally, hypoxia significantly increased HIF-1α transcript levels in MRC-5 fibroblast cells and A-427 tumor cells." (PMID 32596143, 2020). "Due to few samples in stratified tumor subtype categories, we did not perform a correlation analysis between miRNA and HIF-1α in each tumor subtype and stage." (PMID 32707933, 2020). "IL32 was independently and positively associated with Ki67, HIF1A, and ACTA2 and negatively with TJP1 in tumors and with IL10Ra and BCLxL in non-transformed tumor-adjacent tissue." (PMID 33020452, 2020). "Therefore, we examined the effects of FBX8/HIF-1α, FBX8/CDK4, and FBX8/C-Myc, on tumor angiogenesis, cell cycle progression, cell proliferation, and stem cell potential, respectively." (PMID 32796813, 2020). "Consistent with the in vitro results, mice injected with ESM-1-overexpressing 4T1 cells exhibited significant increases in tumor volume, lung metastasis, metastasis-related molecules (VEGF, MMP-9, ICAM-1, and VCAM-1), and transcription factors (HIF-1α, phospho-NF-κB, and phospho-STAT-3)." (PMID 32466580, 2020). "In the present study, we have analysed HIF1α, EGFR and pEGFR protein expression and EGFR gene copy number in HPV-negative LA-HNSCC patients to establish a correlation between these tumour biomarkers and treatment response to cisplatin radiation and nimotuzumab plus cisplatin radiation." (PMID 32939054, 2020). "Tumor xenografts experiments revealed that PVT1 level correlated with miR-519d-3p and HIF-1A level." (PMID 32201527, 2020). "Moreover, high CD74 co-expression with immunosuppressive genes VEGFA and HIF1α and hematopoietic marker CD45 and tumor marker MultiKRT demonstrates that CD74 is expressed by both the tumor cells and the immune cells." (PMID 33228231, 2020).